ARG1 (arginase 1)
Diseases named in the same sentence as ARG1 in open-access papers (continued):
Sharing a sentence is not in itself a finding about the gene and the disease.
tumor (continued). "In contrast, we observed a significant reduction in M1 gene markers in the spleens of tumor-bearing mice, whereas inconsistent changes were observed for the M2 markers (higher levels of Arg1 and lower levels of CCL2 and CD163)." (PMID 37628775, 2023). "When examining paired samples of HNSCC tissue and plasma, an additional discrepancy was discovered: all patients with low tumor and high plasma Arg-1 levels had nodal metastases and developed recurrence." (PMID 38001706, 2023). "Consistent with the mRNA-based results, ARG1 protein expression was associated with CD45+ cells and was significantly elevated in 66cl4 tumours." (PMID 37980483, 2023). "Nevertheless, Zhou et al42 revealed that PMN‐MDSCs were able to inhibit tumor infiltration of IFN‐γ+TNF‐α+CD8+ T lymphocytes through the expression of Arg‐1." (PMID 37326143, 2023). "Among the differentially expressed genes, arginase 1 (ARG1) showed a unique expression pattern in tumour-infiltrating myeloid cells that correlated with the metastatic capacity of the tumour." (PMID 37980483, 2023). "With respect to the gene expression profile, CCL21 increased the expression of tumor-supportive genes such as Vegfa, Mrc1, Arg1, and Cd274 (PD-L1) in microglia, as well as in BMDMs that also showed increased expression of Il-10 and Tgfβ1." (PMID 37314567, 2023). "When ARG1 peptide vaccine was tested in mice, the data indicated enhanced immune response against tumor cells." (PMID 37185755, 2023). "Several mechanisms facilitating tumor escape from immune surveillance have been described, among which Arginase-1 (Arg-1) plays an important role." (PMID 38001706, 2023). "Arginase 1 (Arg1) and fibronectin-1 (Fn1) are markers of immunosuppressive macrophages that potentiate tumor growth." (PMID 37461742, 2023). "Although these cells displayed a similar tumour peripheral distribution as Arg1 mRNA-containing cells, the ARG1 protein-containing cells also infiltrated deeper into the tumour core." (PMID 37980483, 2023). "Macrophage metabolism of apoptotic cell-derived arginine promotes continual efferocytosis and resolution of injury, and activation of ARG1 suppresses dendritic cell-mediated anti-tumor immunity." (PMID 36639644, 2023). "All but one (ARG1) of the proteins with significantly lower expression at baseline in the p16+ tumour group also showed lower expression at 12 months—that is, PTN, TNFRSF12A, CD28, and CD70." (PMID 36835246, 2023). "In contrast, IL-4/IL-13 stimulation promotes the M2 phenotype that is characterized by the upregulated expression of arginase 1 (Arg1), which metabolizes L-arginine to various tumor-supporting factors (e.g., L-ornithine and polyamines)." (PMID 37108657, 2023). "The production and release of tumor-derived exosomes (TEX) represent a way for the Arg-1 export from the tumor cells to peripheral tissues or blood." (PMID 38001706, 2023). "In tumor microenvironments, neutrophils infiltrate different cancers and express inhibitory immune checkpoints, including ARG1 and PD-1/PDL1, which restrict immune surveillance of malignant cells." (PMID 38239507, 2023). "Future research would focus on gaining deeper mechanistic insights into how metastatic tumours module myeloid cells' phenotype and how ARG1-positive myeloid cells influence tumour progression and response to anti-cancer therapies." (PMID 37980483, 2023). "Consistently, factor analyses of other lineages revealed overlapping differential gene programs between tumor and injury models, including Treg cell depletion-induced gene programs in Arg1+ macrophages and IC signatures in Col14a1 matrix fibroblasts." (PMID 37127830, 2023). "The combined addition of L-arginine + nor-NOHA significantly inhibited arginine-dependent tumor growth (p = 0.0007), suggesting that Arg-1 enzymatic activity (i.e., arginine catalysis) and high Arg-1 expression levels regulate tumor cell proliferation." (PMID 38001706, 2023).
tumor (continued). "Tumor Arg-1 expression levels were high (i.e., above median) in 16 patients (8 with low and 8 with high plasma Arg-1 levels) and were low (i.e., below the median) in 15 patients (8 with low and 7 with high plasma Arg-1 levels)." (PMID 38001706, 2023). "We conclude that exosomes can export Arginase-1 from the tumor to the periphery for further immunosuppression." (PMID 38001706, 2023). "Analyzing myeloid pro-tumor functions, a different gene profile characterized by distinct molecular features, such as pSTAT3 and arginine-1 (ARG1), was found in the immune suppressive monocytes of PDAC." (PMID 37872395, 2023). "Some key enzymes of neutrophils, such as Arg1 and Nos2, are directly or indirectly inhibited to reduce their tumor-promoting effects." (PMID 37496019, 2023). "Tumor Arg-1 expression was monitored via immunohistochemistry while plasma Arg-1 levels via ELISA in 37 HNSCC patients." (PMID 38001706, 2023). "PepO-primed M2 macrophages decreased the expression of tumor-supportive molecules like Arg-1, Tgfb, Vegfa and IL-10, and increased the expression of iNOS, Cxcl9, Cxcl10, TNF-α and IL-6 to inhibit TNBC growth." (PMID 37925462, 2023). "The hypoxic TME increases HIF-1α expression in tumor cells, which in turn stimulate inducible nitric oxide synthase (iNOS) and arginase (ARG1 and ARG2) synthesis." (PMID 38259478, 2023). "The ARG1 protein expression levels of primary tumor were high compared with the normal tissues of CRC patients." (PMID 36639644, 2023). "Since we found high levels of myeloid cells containing ARG1 in the metastatic tumour, we analysed the cells isolated from the BM, spleen, blood, and lungs for the presence of these cells." (PMID 37980483, 2023). "The relationships between the abundance of Rothia genus, the level of norvaline, and the level of Arg-1 in breast tissue tumor requires further studies to understand the mechanism of the influence of Rothia and the metabolite norvaline on tumor growth." (PMID 36983633, 2023). "The immunosuppressive effect of tumor-infiltrating MDSCs was mainly due to increased Arg1 transcription and production of nitric oxide by HIF-1α." (PMID 36817434, 2023). "An increase in tumor myeloid Arg1 expression has been reported in other cancers, including renal cell carcinoma, breast, colon, and lung cancer." (PMID 36727849, 2023). "In contrast, M2-type macrophages produce anti-inflammatory cytokines, such as interleukin (IL)-10 and upregulate the expression of arginase-1, which can promote tumor cell proliferation, metastasis, invasion and angiogenesis, inhibit immune response." (PMID 37993261, 2023). "We also observed that overexpression of ARG1 or AGMAT after AAV injection was detected only in non-tumor liver tissue of L-dKO mice, whereas the few “escaper” tumors that appeared expressed low levels of ARG1 and AGMAT." (PMID 37804830, 2023). "ARG1 is expressed by MDSCs and activated TAMs, which worsens the consumption of arginine and fosters a milieu harmful to T-cell survival, resulting in tumor immunosuppression." (PMID 36677919, 2023). "Tumor inhibition correlated with a decrease in a subtype of protumor macrophages and an increase in a subset of Arg1-positive macrophages expressing antitumor gene signatures." (PMID 36639681, 2023). "In both the tumours, lymphoid cells contributed to 1.5% of all ARG1-positive cells and expressed relatively low levels of ARG1." (PMID 37980483, 2023). "In summary, low-dose SNAP treatment induced CD8+ T cell activation and regulated Arg1-expressing macrophages with antitumor properties in the tumor microenvironment." (PMID 36639681, 2023). "ARG1 protein levels were significantly higher in the plasma of mice bearing 66cl4 tumours compared to plasma from healthy and 67NR tumour-bearing mice." (PMID 37980483, 2023). "Expression of Arg-1 leads to under-expression of p-AKT, resulting in deactivation of the AKT signaling pathway in BC cells; therefore, arg-1 acts as a tumor suppressor in BC." (PMID 36983633, 2023).
tumor (continued). "Even though ARG1-positive cells were found almost exclusively inside the metastatic tumour, ARG1 protein was also present in the plasma." (PMID 37980483, 2023). "Patients with high tumor Arginase-1 levels had better clinicopathology and prognosis, while patients with high plasma Arginase-1 levels had unfavorable clinicopathology." (PMID 38001706, 2023). "Arg-1 is expressed in various cell types, particularly in immune cells, liver, kidney, and certain tumor cells." (PMID 38075277, 2023). "PepO treatment dramatically increased tumor infiltrating macrophages (F4/80+) and iNOS+ M1 macrophages while decreasing Arg-1+ M2 macrophages in TME." (PMID 37925462, 2023). "Even though ARG1 expression was induced upon immune cell infiltration into the tumour, a small number of ARG1-positive myeloid cells were also found in the lungs, which is the main metastasis site for 66cl4 tumours." (PMID 37980483, 2023). "Flow cytometry of single-cell suspensions was used to score CD11b+/Ly6G+ intermediate and ARG1 positive cells from different organs of control and tumour-bearing mice." (PMID 37980483, 2023). "Circulating Arg-1+ exosomes represent a mechanism of active Arg-1 export from the tumor to the periphery." (PMID 38001706, 2023). "To evaluate the spatial distribution of Arg1 mRNA and ARG1 protein, we performed in situ hybridisation and immunohistochemistry on paraffin-embedded tumour tissue sections." (PMID 37980483, 2023). "Another TKI, cabozantinib, significantly decreased the MDSC numbers in both the tumor site and spleen, restraining ARG‐1 expression and assisting the recruitment of CD8+ T cells into the TME." (PMID 37547175, 2023). "In line with the RNA sequencing-based data, Arg1 mRNA-containing cells were abundant in the 66cl4 tumours." (PMID 37980483, 2023). "We identified multiple clusters of mononuclear phagocytes including macrophages (Mac), several of which expressed genes associated with pro-tumour subtypes, including CD206 (Mrc1), Arg1, Retnla, Fn1 and C1qa50,51." (PMID 37605008, 2023). "By contrast, pro-tumor/anti-inflammatory TAMs have a phenotype associated with expression of CD206, ARG1, PD-L1 and secretion of IL10." (PMID 37469718, 2023). "In the context of HNSCC, tumor cells appear to package Arg-1 into exosomes and transport it to the periphery and to distant cells, thereby regulating Arg-1 levels in the producing tumor cells." (PMID 38001706, 2023). "GBM CM-treated microglial cells showed similar increased expression of tumor-supporting proteins such as Arg1, that was abrogated by CCL21-blocking Abs." (PMID 37314567, 2023). "Rbm39 knockdown reduced tumor burden in L-dKO mice, and as observed upon ARG1 or AGMAT overexpression and Asns knockdown, Rbm39 knockdown was detected only in non-tumor tissue." (PMID 37804830, 2023). "They stated that CENDE stimulated TAMs to produce IL-10 and Arginase-1, which then induced M2 polarization of TAMs to mediate the pro-tumor effect of CENDE." (PMID 36776333, 2023). "On the other hand, class I HDAC inhibition has been reported to support anti-tumour response by dampening ARG-1, iNOS, and COX-2 levels in MDSCs as well as altering the release of cytokines/chemokines." (PMID 36161514, 2023). "In line with our previous results, the drug-mediated SPHK1 inhibition resulted in a strong reduction of Arg1 and Msr1 expression in the tumor-microglia co-culture." (PMID 36672428, 2023). "Tadalafil decreased tumor Arg-1 and lowered both granulocytic and monocytic MDSC in a murine colon cancer model." (PMID 36230888, 2022). "Following culture, both splenic and tumor M-MDSCs treated with αIL-4/13Ab-ILC2-SNT had decreased Arg1 expression compared to conAb-ILC2-SNT-treated M-MDSCs, indicating that intestinal ILC2-derived IL-4 and IL-13 can promote Arg1 expression in M-MDSCs." (PMID 35658010, 2022).
tumor (continued). "The TAMs are classified into the pro-inflammatory M1 macrophages and immunosuppressive M2 macrophages, and M2 polarization is seen during tumor development and characterized by the upregulation of arginase-1 (Arg1)." (PMID 35251971, 2022). "Similar to F4/80lowLy6Clow macrophages in tumor tissue, F4/80lowLy6Clow macrophages sorted from the uIRI kidney cortex highly expressed Arg1 and Vegfa compared to F4/80highLy6Clow macrophages." (PMID 36470862, 2022). "This change was also evidenced by the significant decreases in IL-6 and Arginase-1 which confirm a shift away from pro-tumor immune phenotypes." (PMID 35513776, 2022). "IL-9 also changes expression of genes in these populations, including the Arg1 gene that is critical for the pro-tumor activity." (PMID 35778404, 2022). "The current study describes what we believe to be a novel mechanism by which ARG1 mRNA expression is regulated in neutrophils in cancer and highlights the central role that neutrophil lineage cells play in the suppression of tumor-infiltrating lymphocytes." (PMID 36377658, 2022). "The ratio of MDSCs from bone marrow, blood, spleen and tumor tissue and the mRNA levels of Arg1 and iNOS from splenic MDSCs were found to decrease in the group co-treated with anti-PD-1 and DIM compared with the single treatment group." (PMID 35773674, 2022). "PMN-MDSCs account for about 70-80% of MDSCs in tumor models; secrete arginase 1 (ARG1) and upregulate NADPH which contributes to ROS production that inhibits immune cells function and activate of STAT3 signaling pathway." (PMID 35140716, 2022). "CML-MSCs enhance immunosuppressive MDSCs production and aggregation, promoting tumor progression via upregulating immunomodulatory arginase-1 (Arg-1), IL-6, IL-1β, COX-2, and TNF-α in MDSCs and inhibiting anti-tumor immunity." (PMID 35842634, 2022). "Three 20x high-density fields were taken of each tumor section, and Arg1 (as a marker of M2 TAMs), CD86 (as a marker of M1 TAMs), and CD8 (CD8+ Tc) positivity was evaluated using AI trainable WEKA segmentation." (PMID 35634303, 2022). "Pharmacological inhibition of extracellular ARG1 has shown antitumour efficacy in various syngeneic tumour models, however, the importance of ARG2 as a therapeutic target has only been demonstrated by genetic deletion studies." (PMID 36010962, 2022). "Here, the authors show that IL-9 promotes the expansion of pulmonary macrophages and that targeting the IL-9R/arginase 1 axis restricts tumor growth, thus identifying this cytokine pathway as a potential therapeutic target." (PMID 35778404, 2022). "Tumor lysate of the triple therapy also exhibited 5.6 time higher expression of iNOS (N1 marker) and 33% lower expression of Arg1 (N2 marker) than those of the IRE + αPD1 group, respectively." (PMID 35128843, 2022). "The results of these experiments indicate slower tumor progression and prolonged animal survival when myeloid cells lack ARG1." (PMID 36385153, 2022). "In hypoxic conditions, a metabolic shift of tumor cells leads to an accumulation of lactic acid which promotes Vegf and Arg1 expression by TAMs." (PMID 36679900, 2022). "Both macrophage subpopulations expressed enhanced arginase-1 (ARG1) transcription, a marker for M2-polarized macrophages and tumor-associated macrophages (TAM); however, CD11b+F4/80hiMHCIIlow was the major source of Arginase1 in the tumors." (PMID 35163097, 2022). "Tumor-derived IL-8 induces neutrophils to secret arginase-1, resulting in arginase depletion and the establishment of an immunosuppressive TME." (PMID 36230676, 2022). "Tumor M-MDSCs expressed Arginase 1 (Arg1), consistent with a suppressive phenotype, and the genes encoding the IL-4Rα and IL-13Rα1 receptor subunits, suggesting their potential ability to respond to ILC2-derived cytokines IL-4 and IL-13." (PMID 35658010, 2022).
tumor (continued). "ARG1 consumes L-arginine, which is necessary for cytotoxic T lymphocytes to exert anti-tumor activity, and produces polyamines with strong immunosuppressive effects." (PMID 35468826, 2022). "The platelet count, tumor size, number of lesions, and plasma ARG1 levels of the patient were 67.7×109/L, approximately 7.42 cm, 2, and 22.6 ng/mL, respectively." (PMID 36212404, 2022). "The expression of M2 markers, including ARG1, IL10 and CD163 was higher in MADCAM1P270Q-reprogrammed tumor-associated macrophages (TAMs) and MADCAM1D242N-reprogrammed-TAMs, but lower or same in MADCAM1WT-reprogrammed-TAMs compared with control." (PMID 35449126, 2022). "Myeloid-derived suppressor cells (MDSCs) are immature myeloid cells that mediate immunosuppression by JAK3/STAT3-dependent secretion of reactive oxygen species (ROS) and arginase-1 (ARG-1) into the tumor microenvironment." (PMID 35055124, 2022). "Inhibitors such as nor-N-hydroxy-L-arginine and amino-guanidine successfully downregulate ARG-1 and iNOS expression in MDSCs, restoring T cell function and delaying tumor progression." (PMID 35328639, 2022). "There was a substantial reduction of Arg1 expression in lung IM populations in tumor-bearing Il9r−/− mice." (PMID 35778404, 2022). "In conclusion, the anticancer effects of 1,8-cineole and ellagic acid were demonstrated for the first time through 1) Conserving of liver functions 2) Lessening of HCC tumor markers; alpha-fetoprotein, ferritin, arginase-1, and alpha-L-fucosidase." (PMID 35081125, 2022). "M2 macrophage polarization supports the growth and malignancy of tumors by suppressing the anti-tumor immune responses of the host by secreting immunosuppressive molecules, such as arginase 1 (Arg1) and the cytokine IL-10." (PMID 36297535, 2022). "The presence of lactic acid alone can induce the expression of VEGF and ARG1 in macrophages, thereby promoting tumor growth and metastasis." (PMID 35456426, 2022). "The increased expression of Pvt1 which is induced by HIF-1α under hypoxia causes the down-regulated expression of Arg-1 and ROS in PMN-MDSCs, and assists T cells to suppress tumor growth in tumor-bearing mice." (PMID 36569895, 2022). "These molecules correspond to the ADI or Arg1 enzymes conjugated to polyethylene glycol (delivered in order to consume extracellular arginine), favoring its depletion into the tumor microenvironment." (PMID 35159363, 2022). "One of the main metabolic pathways in macrophages shown to influence tumor growth is amino acid metabolism, and protumoral TAMs frequently highly express arginase-1." (PMID 34876704, 2022). "Although both ADI-PEG20 and IR monotherapy increased tumor microglial/macrophage infiltration, their expression of Arg1 differed." (PMID 35113813, 2022). "Seventy-five percent of the genes that were differentially expressed between spleen and tumor MDSCs were common to both subtypes, including the classical tumor MDSC markers Arg1 (>100-fold increased) and Nos2 (16- to 32-fold increased)." (PMID 36480485, 2022). "Further studies revealed that after MDSCs metastasized to the tumor, their exposure to the inflammatory and hypoxic tumor microenvironment clearly resulted in Arg1 and inducible nitric oxide synthase (iNOS) and decreased ROS production." (PMID 36505462, 2022). "In epithelial ovarian cancer, increased ARG1 expression has been found to contribute in tumor growth and immune suppression, while the blocking of ARG1 mitigated ARG1-mediated tumor progression and immune response." (PMID 36091114, 2022). "They found that tumor cells use TEX as vehicles to carry over long distances and deliver ARG1 to immune cells to mitigate the anti-tumor immune responses." (PMID 35163380, 2022). "These “M2-like” TAMs produce Arginase-1+ exosomes in the tumor microenvironment, inducing the proliferation of GBM tumors, further augmenting pro-tumor functions." (PMID 36428642, 2022).